TMPRSS6 (transmembrane serine protease 6)
Diseases named in the same sentence as TMPRSS6 in open-access papers (continued):
Sharing a sentence is not in itself a finding about the gene and the disease.
inflammatory bowel disease (1 paper, 2022). A spectrum of small and large bowel inflammatory diseases of unknown etiology. "One Mendelian randomization study measured the causal associations of iron status with gout, rheumatoid arthritis, and inflammatory bowel disease using HFE and TMPRSS6 genetic variants as instrumental variables for exposure." (PMID 36295058, 2022).
malaria (1 paper, 2026). Malaria is a serious and sometimes fatal disease caused by a parasite that commonly infects a certain type of mosquito which feeds on humans. "We used a multilayered approach combining clinical data from Malawian pregnant women (n = 711) in the REVAMP trial, a genetic mouse model [Tmprss6-knockout (KO)], and in vitro Plasmodium falciparum cultures to clarify iron-malaria associations." (PMID 41758949, 2026).
metabolic syndrome (1 paper, 2012). A cluster of metabolic risk factors for CARDIOVASCULAR DISEASES and TYPE 2 DIABETES MELLITUS. "For instance, TMPRSS6 variants were significantly associated with ferritin and risk of type 2 diabetes in Chinese, while ferritin itself was an independent risk factor for metabolic syndrome and type 2 diabetes." (PMID 22719963, 2012).
metastatic disease (1 paper, 2024). "In conclusion, the presented work identified the seven genes EMILIN3, MTA1, SV2B, TMPRSS6, ACVR1C, NFAT5 and SMC3 associated with the formation of colorectal BM during the course of disease but not with liver metastasis or non-metastatic disease." (PMID 38558282, 2024).
myocardial infarction (1 paper, 2013). Gross necrosis of the myocardium, as a result of interruption of the blood supply to the area, as in coronary thrombosis. "Gdf15 inhibits leukocyte integrin activation thus reducing inflammatory cell recruitment after myocardial infarction, a finding in agreement with the reduced leukocytes recruitment observed in LPS-treated Tmprss6 KO mice." (PMID 23922777, 2013).
neuroblastoma (1 paper, 2024). Neuroblastoma (NB) is the most common solid, extracranial childhood tumor. "In the present study, we found that Tmprss6 markedly inhibited mouse neuroblastoma N2a (neuro-2a) cell proliferation and tumor growth in nude mice." (PMID 38218852, 2024). "In addition, we also investigated the downstream effects of Tmprss6 activity in human neuroblastoma cell lines, SH-SY5Y." (PMID 38218852, 2024). "Here, we evaluated the role of Tmprss6 in a neuroblastoma cell line and its derived tumors." (PMID 38218852, 2024).
neuronal tumor (1 paper, 2024). Neuronal brain tumors are an uncommon group of central nervous system tumors that arise from cells with neuronal differentiation. "Our results identify Tmprss6 as a new target for inhibiting the growth of neuronal tumors." (PMID 38218852, 2024). "Thus, we propose Tmprss6 as a candidate target for inhibiting neuronal tumor growth." (PMID 38218852, 2024).
ovarian serous cystadenocarcinoma (1 paper, 2021). A malignant serous cystic epithelial neoplasm arising from the ovary. "A higher expression of TMPRSS6 or CLDN10 individually could be detected in other tumors (B respectively), while a higher combined expression was observed in ovarian serous cystadenocarcinoma (OV), thyroid carcinoma (THCA), and uterine corpus endometrial carcinoma (UCEC) apart from LUAD." (PMID 35178045, 2021).
Sepsis (1 paper, 2021). Sepsis is defined as life-threatening organ dysfunction caused by a dysregulated host response to infection. "Single-SNP MR analyses showed that SNPs rs1800562 (HFE) and rs855791 (TMPRSS6) were associated with a significant effect of serum iron or transferrin saturation on sepsis, while SNPs rs1800562 (HFE) and rs2413450 (TMPRSS6) were significantly related to the causal effect of ferritin on sepsis." (PMID 34869523, 2021).
Splenomegaly (1 paper, 2021). Abnormal increased size of the spleen. "The Tmprss6-ASO dose used in this study was effective in significantly lowering circulating red blood cell parameters without detrimental effect on splenomegaly." (PMID 34890402, 2021).
triple-negative breast carcinoma (1 paper, 2024). An invasive breast carcinoma which is negative for expression of estrogen receptor (ER), progesterone receptor (PR), and human epidermal growth factor receptor 2 (HER2). "Multiple clinical studies have shown that Tmprss6 levels are decreased in tumor progression, while low gene expression correlated with poor prognosis in triple-negative breast cancer." (PMID 38218852, 2024).
cancer (11 papers, 2014 to 2024). A tumor composed of atypical neoplastic, often pleomorphic cells that invade other tissues. "Although Tmprss6 is well known for its association with some types of cancer, surprisingly little is known about the mechanisms by which it is involved in the development and growth of cancer, especially in the molecular control of the cell cycle and apoptotic processes in tumor tissues." (PMID 38218852, 2024). "We propose Tmprss6 as a new candidate target for inhibiting neuronal tumor cell proliferation and mediating apoptosis in cancer." (PMID 38218852, 2024). "TMPRSS6 isoform expression analysis in HCC cell lines also emphasizes the potential role of functionally altered TMPRSS6 isoform 3 in cancer, as there are discrepancies between HCC cells lines and healthy human liver samples." (PMID 30135444, 2018). "Others have found that variant forms of TMPRSS6 were associated with increased risk of childhood ALL in males, so it may be common to multiple cancer types." (PMID 27898674, 2016). "Finally, we discovered that the 12 IMRGs expression had significant differences, among which SFXN3, TFR2, TMPRSS6, HMOX1, and LCN2 expressions were elevated in the cancer group, and SCARA5, LTF, STEAP2, SLC39A14, CP, ALAS2, and TF were low expressed in the tumor group." (PMID 37361050, 2023). "However, it is not clear whether the role of TMPRSS6 in cancer progression is due to its ability to cleave extracellular matrix component such as fibronectin or due to a modification of iron parameters in cancer cells." (PMID 24966834, 2014).
tumor (8 papers, 2007 to 2025). "TUNEL staining further confirmed that overexpression of Tmprss6 induced the production of apoptotic bodies in tumor tissues." (PMID 38218852, 2024). "Similar results were obtained when analyzing the expression of CLDN10 and TMPRSS6 in LUAD tumor samples." (PMID 35178045, 2021). "To examine whether Tmprss6 overexpression can affect NB tumor growth, we subcutaneously implanted neuro-2a cells into nude mice." (PMID 38218852, 2024). "An interesting observation is that expression of neither CLDN10 nor TMPRSS6 were associated with any immune population, suggesting that they are present in the primary tumor and not in the stromal compartment." (PMID 35178045, 2021). "Patients whose tumour had high expression of MAP1LC3A, SNCA, and MAPT and low expression of CDK1, AP1S1, CASP3, TMPRSS6, and GSK3B inferred better overall survival than all other patients." (PMID 38642129, 2024). "We confirmed the continuous overexpression of Tmprss6 and FLAG in the process of tumor growth by western blot analysis." (PMID 38218852, 2024). "Stromal ECM and stromal cells were negative for TMPRSS6 but were weakly expressed in the cytosol of primary tumour cells, with intense staining of small clusters of cells that were in contact with the surrounding stroma." (PMID 40998421, 2025).
infection (4 papers, 2021 to 2024). The state of being infected such as from the introduction of a foreign agent such as serum, vaccine, antigenic substance or organism. "The expression of the transmembrane serine protease 6 (TMPRSS6) gene in the mock infection-challenged AT2s showed the highest correlation (r2 = 0.918; FDR-corrected p-value = 1.51 × 10−5) with SARS-CoV-2 viral load measures." (PMID 38474333, 2024). "As stated in the results, the pre-infection expression of the TMPRSS6 gene showed the highest positive correlation with SARS-CoV-2 viral load in 10 AT2 lines." (PMID 38474333, 2024). "Interestingly, the observed HCV-mediated induction of hepcidin expression was accompanied by a profound decrease of its negative regulator matriptase-2 (TMPRSS6) by at least 80% towards the later stages of infection, as compared to the mock-infected controls." (PMID 34571900, 2021). "Loci exhibiting the strongest stimulation by infection and repression by remdesivir included several proteases (TMPRSS4, TMPRSS6, TMPRSS11D, TMPRSS11E) closely related to TMPRSS2, a host factor during SARS-CoV-2 receptor-mediated endocytosis." (PMID 37205380, 2023).
autosomal recessive inherited disease (1 paper, 2022). "IRIDA is considered an autosomal recessive inherited disease, with most patients described as harboring biallelic exonic pathogenic variants in TMPRSS6." (PMID 35893046, 2022).
hematologic disease (1 paper, 2017). "We report here the first rare coding variant of TMPRSS6 (p.V280L/p.V289L) associated with RBC traits in individuals unselected for hematologic disease." (PMID 28787443, 2017).
retinopathy (1 paper, 2013). "Moreover, for any retinopathy, there were several nominally significant associations with SNPs close to the ANK1, SLC30A8, MTNR1B, TMPRSS6 and HK1 loci." (PMID 24244560, 2013).
TMPRSS6 also shares sentences with these, for which no sentence is quoted: anemia (31 papers); celiac disease (3); iron (3); iron overload diseases (3); liver cancer (3); lung carcinoma (2); Polycythemia Vera (2); acute leukemia (1); Alpha-thalassemia (1); autism spectrum disorder (1); Bernard-Soulier syndrome (1); Cirrhosis (1); colorectal cancer (1); diabetes (1); Diamond-Blackfan anemia (1); diseases of the esophagus (1); end-stage renal disease (1); fibrodysplasia ossificans progressiva (1); gallbladder cholesterolosis (1); genetic disorder (1); glioma (1); glossitis (1); Glucose intolerance (1); Hypercholesterolemia (1); Insulin resistance (1); iron metabolism disorder (1); ischaemic heart disease (1); leukemia (1); neurologic diseases (1); Nonalcoholic Fatty Liver Disease (1).
A further 5 diseases each share a sentence with TMPRSS6 in 1 paper.